IRF1 (interferon regulatory factor 1)
Diseases named in the same sentence as IRF1 in open-access papers (continued):
Sharing a sentence is not in itself a finding about the gene and the disease.
tumor (continued). "In summary, our findings identify for the first time that IRF-1 tumour suppressor as a novel HPV16 E6-interacting protein." (PMID 33076322, 2020). "The anti-proliferative action of IRF1 is well studied and contributes to tumour suppressor activity." (PMID 30854564, 2019). "IRF1 is also known as tumor suppressor, capable to avoid tumor cell growth, and stimulate an immune response against tumor cells." (PMID 31867044, 2019). "IRF-1 is a crucial TF that regulates the immune response, immune cell development, cell growth, tumor suppression, autophagy, and apoptosis in mammalian cells." (PMID 31118037, 2019). "The SUMO modification level of IRF-1 was significantly increased in tumor cells by screening for SUMO protein." (PMID 31753025, 2019). "Further IHC analysis showed that the tumours in the Lv-IRF-1 group treated with Dox exhibited significantly increased IRF-1 expression and significantly reduced β-catenin and C-Myc levels compared with those in the Lv-IRF-1 and Lv-Null + Dox groups." (PMID 31186404, 2019). "Irf1 is a transcriptional regulator and tumor suppressor that suppresses tumor cell growth and stimulates an immune response against tumor cells." (PMID 30621584, 2019). "IFNγ also induces synthesis of PD-L1 transcription factor IRF1 and expression of checkpoint inhibitors including PD-L1 and PD-L2 on the surface of tumor, macrophages and dendritic cells." (PMID 31533832, 2019). "IRF1 is described to be able to directly induce NO synthase and is therefore an important factor to eliminate tumor cells." (PMID 30647851, 2018). "Consistently, XAF1 and IRF-1 decreased the colony-forming ability of tumor cells in a highly IRF-1- and XAF1-dependent manner, respectively." (PMID 30042418, 2018). "In the present study, we demonstrate that XAF1 forms a feedback loop with IRF-1 under stressful conditions and evokes its tumor suppression effect in a highly IRF-1-dependent fashion." (PMID 30042418, 2018). "Induction of MHCI contributes to the long-known antitumor potential of IRF-1 enhancing tumor antigen presentation that improves the efficacy of the cell-mediated antitumor immune response." (PMID 29599126, 2018). "Anti-apoptotic proteins of the GAGE family (a group of highly related tumor antigens) can bind and stabilize NPM/B23, which is indirectly involved in loss of IRF-1 function." (PMID 29599126, 2018). "The expression of IFNAR1 was correlated with that of IRF1 in the tumor tissue of adenocarcinoma and those of IRF1 and IRF7 in the normal tissue of SCC." (PMID 30305853, 2018). "The results delineate increased expression of angiogenic and oncogenic markers CXCR4, SDF-1, and decreased expression of tumor suppressor genes, IRF1, LDOC1, and FOXO3 in CP patient tissues." (PMID 30413788, 2018). "Upstream regulatory analysis implicated increased activation of STAT1 and IRF1, and inhibition of Interferon-stimulated transcription mediated by IRF4, in hot tumours." (PMID 30104673, 2018). "These support that XAF1 inhibits NF-κB tumor-promoting function by reinforcing IRF-1 interaction with a subset of coregulated target promoters." (PMID 30042418, 2018).
tumor (continued). "Collectively, these demonstrate that XAF1 modulates IRF-1 function to stimulate and repress transcription of proapoptotic and tumor-promoting genes, respectively, thereby provoking its tumor suppressive function." (PMID 30042418, 2018). "The resulting IRF-1 protein lacks the ability to bind DNA and its tumor-suppressing activity is consequently lost." (PMID 29599126, 2018). "IRF-1 also acts as a tumor suppressor by modulating expression of genes involved in apoptosis, cell-cycle control, and angiogenesis." (PMID 30042418, 2018). "Willman and colleagues proposed that a tumor suppressor gene must be located in the common deleted segment (5q31), and eventually succeeded in mapping IRF-1 to band 31.1 of chromosome 5 using fluorescence in situ hybridization with a 19-kb IRF-1 probe." (PMID 29599126, 2018). "The PDL1 expression on tumor cells can be upregulated by intrinsic oncogenic signaling pathways or by surrounding T cells through the IFNγ/STAT1/IRF1 pathway and chronic type I IFN exposure." (PMID 30305853, 2018). "To elicit the role for the IRF-1−XAF1 interplay in vivo, we carried out mouse tumor xenograft assays using sh-Control and sh-IRF-1 sublines of HCT116 (Tet-XAF1) cells." (PMID 30042418, 2018). "It was reported that Ras/MEK activation increases tumor resistance to antiviral effects of IFNs by downregulating IRF-1 and that XAF1 transcription is repressed by Ras/MEK35–37." (PMID 30042418, 2018). "In the present study, we identified that XAF1 attenuates NF-κB-mediated transcription of tumor-promoting genes by facilitating IRF-1 repression of p65/RelA-mediated transcription." (PMID 30042418, 2018). "IRF1 is a well-known transcription activator of the genes induced by interferons α, β, and γ thereby inhibits the cell growth and suppresses tumor progression." (PMID 28592284, 2017). "Expression of IRF-1 and PD-L1 in archival pre-treatment formalin-fixed, paraffin-embedded tumor samples were assessed by the AQUA method of quantitative immunofluorescence." (PMID 28331615, 2017). "IRF-1 functions both as a tumor suppressor and regulator of immune response, and is required for IFNγ-mediated TH1 differentiation in CD4+ T cells." (PMID 28642803, 2017). "Multiple lines of evidence have also emphasized the influence of IRF1 on the immune response, DNA damage, apoptosis regulation and tumor suppression." (PMID 27149165, 2016). "Overexpression of IRF2, which antagonizes IRF1, promotes transformation of NIH 3T3 cells, suggesting that IRF1 is a tumor suppressor." (PMID 27809273, 2016). "IRF-1 has been referred to as the “master promoter”, due to its capacity to activate a variety of tumor suppressor genes." (PMID 27191889, 2016). "This was confirmed in GC tissues, where expression of miR-23a was frequently higher, whereas IRF1 was downregulated compared to gastric non-tumor tissues." (PMID 27011182, 2016). "Interferon regulatory factor-1 (IRF-1) is a tumor-suppressor in HCC and its down-expression would help HCC tumors evade death." (PMID 27917899, 2016). "IRF-1 is described as the “master promoter”, as it is involved in tumor growth regulation through a variety of mechanisms." (PMID 27191889, 2016). "Our work shows a cross-talk between macrophages and L929 cells where IRF-1 and NOproduction work against tumor cells by inducing L929 cell death invitro and control of tumor growth in vivo." (PMID 25659093, 2015). "Our results indicate that IRF-1 is a masterregulator of bi-directional interaction between macrophages and tumor cells." (PMID 25659093, 2015). "SFN increased transcriptional activation by IRF-1 (IFN-regulatory factor 1) acting as a tumor suppressor binding to upstream regulatory regions of IFN-1 and IFN-1-induced MHC class I genes." (PMID 25955133, 2015).
tumor (continued). "IRF1 is decreased in cancer tissues and functions in the immune response, apoptosis regulation, DNA damage repair and tumor suppression." (PMID 25658920, 2015). "Overall,IRF-1 was essential for NO production by co-cultures and macrophage tumoricidalactivity in vitro as well as for the control of tumor growthin vivo." (PMID 25659093, 2015). "Our study showed that ARTD9 can inhibit the IFNγ/STAT1-dependent anti-proliferative and pro-apoptotic activities of tumor suppressor IRF1 while simultaneously activating the STAT1/IRF2-mediated anti-apoptotic-pro-survival pathways in HR-subtype DLBCL cells." (PMID 26654227, 2015). "Analysis of IRF1 in diverse cell types, in-vivo models and tumors indicate tumor-suppressor activity." (PMID 26460486, 2015). "Our resultsshowed that IRF-1 is a master regulator of bi-directional interaction betweenmacrophages and tumor cells." (PMID 25659093, 2015). "IRF-1 was required for NO induction, macrophage tumoricidalactivity in vitro and for the control of tumor growth invivo." (PMID 25659093, 2015). "In fact, there was crosstalk between NK cells and tumor cells through the IFN-γ-induced transcription factor IRF-1, which is expressed on tumor cells, supporting the pulmonary attraction and activation of NK cells." (PMID 25674087, 2015). "The transcription factor IRF-1 has been defined as tumor suppressor gene that inhibits cell proliferation enhances apoptosis and controls tumor growth." (PMID 24675692, 2014). "Fourth, IRF1 is required for the BV6-stimulated secretion of inflammatory cytokines and immune response, as IRF1 silencing in tumor cells attenuates cytokine secretion by BV6-treated cells as well as by migration of primary monocytes towards tumor cells." (PMID 25501823, 2014). "Transcriptome sequencing analysis shows that IRF-1 can induce the AS of other genes as well, including those involved in membrane regeneration and repair, microtubule assembly, and tumor suppressor functions." (PMID 24650050, 2014). "IRF1 is required for this interaction of tumor cells with the microenvironment, as IRF1 depletion abolishes BV6-stimulated cytokine secretion and monocyte attraction." (PMID 25501823, 2014). "Our study demonstrates that DTX3L and ARTD9 cooperate as repressors of the tumor suppressor IRF1 in mPCa cells." (PMID 24886089, 2014). "Our ChIP-seq data indicates that the major tumor suppressor activity of IRF1 is the regulation of cell death pathways." (PMID 25893139, 2013). "Conversely, IRF1 expression reverts the phenotype of oncogenically transformed fibroblasts, and IRF-1 enhancing drugs with tumour suppressing properties are currently being developed." (PMID 23915349, 2013). "As we were interested in defining IRF1 pathways important for its’ tumor suppressor activity, we performed analysis of enriched functional categories for the annotated genes bound in control (unstimulated) or IFN-gamma stimulated cells using DAVID." (PMID 25893139, 2013). "IRF1 is a transcription factor involved in interferon signaling and has been shown to harbor tumor suppressor activity." (PMID 25893139, 2013). "In a previous study, we determined that Irf-1 overexpression in VSMCs has an anti-proliferative effect under normal glucose conditions, consistent with the tumor suppressor activity of Irf-1." (PMID 24119616, 2013). "A previous study on IRF-1 identified a tumor suppressive function demonstrating the importance of additional investigation of IRF-1 in oncogenesis regulation." (PMID 23420765, 2013). "In response to OV infection, type I and II IFN secretion by infected cells within the tumor environment (which also includes normal tumor infiltrating cells) leads to the up-regulation of hundreds of ISGs including IRF-1, which up-regulates CIITA expression." (PMID 24062768, 2013).
tumor (continued). "Increasing evidence supports the theory that IRF-1 functions as a tumor suppressor and represses the transformed phenotype." (PMID 24066008, 2013). "Irf-1 displays tumor suppressor activity and is regarded as a negative regulator of cell growth through regulating downstream effector genes." (PMID 24119616, 2013). "Additional studies demonstrate that IRF-1 exhibits tumor suppressor activities in a number of human tumors." (PMID 23420765, 2013). "The tumor suppressor-like activity of IRF-1 was previously demonstrated by oncogenic transformation assays in which the activated c-Ha-Ras, a single oncogene, was introduced to and transformed IRF−/− MEF cells." (PMID 23420765, 2013). "The previous studies discussed reveal that the IRF-1 transcription factor is involved in the regulation of tumor suppression and oncogenesis." (PMID 23420765, 2013). "The association between IRF-1 and BRIP1 further validates the importance of IRF-1 as a tumor susceptibility gene." (PMID 23420765, 2013). "Bioinformatic analysis indicate that rs6295 is located in a binding site for at least two transcription factors; Irf-1 which plays a role in regulating apoptosis and tumor suppression and NRF-2 which regulates cellular oxidative stress." (PMID 22563461, 2012). "Among these genes, let us note IRF1, which is a well-known mediator for cell fate by facilitating apoptosis, and it is also a tumor suppressor." (PMID 22427814, 2012). "Specifically, IRF1 synergizes with NF-kB in reconstituting full MHC-I-restricted tumor antigen processing and antigen presentation to cytotoxic T-cell (CTL) clones." (PMID 23071666, 2012). "The effects of IRF1 on tumor cell proliferation are achieved through the expression of p21WAF cell-cycle inhibitors (inhibiting transition from the G1 to S stage)." (PMID 21437229, 2011). "In contrast, 51% of the reported tumors expressed IRF1 in the nucleus (in more than 50% of the tumor cells), consistent with a potential to represent a transcriptionally active form." (PMID 22295238, 2011). "The first studies to highlight IRF1's role in tumor suppression and cell cycle control were established using IRF1 −/− mouse embryonic fibroblasts (MEFs)." (PMID 22295238, 2011). "Independent of its possible effects on transducing IFN signals, IRF-1 has been defined as a tumor suppressor gene that inhibits cell proliferation or enhances apoptosis in a manner dependent on its transcriptional activity." (PMID 21909274, 2011). "It sustains proper CTL activity and thus ensures tumor surveillance, while also exerting growth inhibitory and tumor suppressing effects via its downstream regulator IRF1." (PMID 22185785, 2011). "The anti-apoptotic effects of NF-kB are balanced in cancer by the tumor suppressor effects of IRF-1 and/or IRF-5 which directly inhibit its cyto-protective activity." (PMID 21569348, 2011). "Primary cultured tumor cells (LMP2-UC) were established from the uterine LMS of LMP2-deficient mice, and then IRF1-overexpressing tumor cells (LMP2-UC-IRF1) were further established by genetic engineering." (PMID 21437229, 2011). "Signal transducer and activator of transcription (STAT) 1, having been activated by IFN-γ, significantly induced expression of tumor suppressors such as interferon regulatory factor 1 (IRF1)." (PMID 21437229, 2011). "The LMP2-UC-IRF1 cells were intracutaneously transplanted into immunodeficient mice (BALB/c nu/nu), and significant inhibiting effects of IRF1 on tumor cell proliferation were observed." (PMID 21437229, 2011). "A decrease in Treg numbers was recently shown to cause an increase in numbers of WNV-specific CD8+ T cells; or (c) IRF-1 regulated the threshold for activation-induced proliferation after antigen recognition, consistent with its tumor suppressor properties." (PMID 21909274, 2011).
tumor (continued). "Historically, IRF-1 has been considered a negative regulator of cell proliferation, which in part explains its tumor suppressive activity." (PMID 21909274, 2011). "Not making a comparison of the normal skin tissue from BCC patients with the tumor specimens for IRF-1 seems to be a limitation of our study." (PMID 20606993, 2010). "IRF-1 was not only expressed in the tumor cells, but also in some inflammatory cells in the surrounding stroma." (PMID 20606993, 2010). "IRF1 is a member of the interferon regulatory transcription factor family, which has been shown to regulate apoptosis and tumor-suppression." (PMID 18466468, 2007). "IRF1 is a member of the interferon regulatory transcription factor family, which regulates apoptosis and tumor-suppression." (PMID 18466468, 2007). "Furthermore, in orthotopic transplantation models using AKP organoids, overexpression of Stat1R274Q and Irf1 significantly inhibited tumor growth and increased CD8+ T cell infiltration." (PMID 41486293, 2026). "Furthermore, single cell sequencing data from GC patients revealed an inverse correlation between the expression of YTHDF1 and YTHDF2 and that of IRF1, particularly within tumor cells, T cells, and macrophages." (PMID 39587835, 2025). "The tumor microenvironment alters the immune response by modulating the splicing of interferon regulatory factor 1 (IRF1), a key transcription factor in Th1 cells, resulting in the production of different IRF1 protein isoforms with altered activity." (PMID 40002189, 2025). "However, research indicated that IRF1 can promote the expression of PD-L1 and enhance tumor cells’ ability to evade recognition and elimination by T cells." (PMID 40342816, 2025). "Targeting IRF1Δ7 to restore full-length IRF1 expression could potentially enhance Th1-mediated anti-tumor immunity." (PMID 40002189, 2025). "In addition, IFN-γ secreted by CD8+ T cells stimulates ASCL4 expression in tumor cells through IRF1, which leads to the upregulation of ferroptosis in tumor cells, improving the immune checkpoint blockade (ICB)-induced antitumor immunity." (PMID 41373022, 2025). "While numerous studies on IRF1 have primarily focused on its effects on tumor invasion and the immune microenvironment, we conducted a "rescue" experiment to evaluate the correlation between IRF1 and HCC proliferation, specifically investigating the involvement of ITLN1 in this regulatory process." (PMID 41218553, 2025). "We observed that the immune cell composition varied between intra-tumor regions, as well as across different tumors and that the inferred activity of the IRF1 regulatory network and the expression of antigen processing and presentation genes were associated with cytotoxic lymphocyte infiltration." (PMID 40894019, 2025). "We then investigated IRF1 gene expression levels when 1p was deleted in NB tumor samples in Xena." (PMID 40082458, 2025). "These expression patterns supported our hypothesis and suggested that the potential antagonistic oncogenic activities of IRF1 may be due to IRF1 having different levels of expression in different cell types of the same tumor." (PMID 40862725, 2025). "Such variation in IRF1 signaling could potentially influence APPG expression levels in tumor cells, affect their antigen processing and presentation capabilities and ultimately impact tumor immunity and TIME type." (PMID 40894019, 2025). "Therefore, interfering with any of the targets on the IFN-γ/IFNGR/JAK/STAT/IRF1 axis will impact PD-L1 expression and ultimately affect resistance to the tumor." (PMID 40178680, 2025). "Our study is unique as we characterized IRF1 expression in all cell types in breast tissue of HER2+ patients in contrast to previous studies that have utilized breast bulk patient samples in toto or tumor epithelial cell lines." (PMID 40862725, 2025).